VCAM1 (vascular cell adhesion molecule 1)
Diseases named in the same sentence as VCAM1 in open-access papers (continued):
Sharing a sentence is not in itself a finding about the gene and the disease.
atherosclerosis (continued). "The levels of biomarkers of endothelial dysfunction and atherosclerosis, such as intercellular adhesion molecule-1 (ICAM-1) and vascular cell adhesion molecule-1 (VCAM-1), are increased in the serum of patients receiving hemodialysis." (PMID 34769353, 2021). "An increase in YKL-40 levels activate endothelial cells to express vascular adhesion molecule-1 (VCAM-1) and intercellular adhesion molecule-1 (ICAM-1), further injuring the vascular endothelial cells, and promoting the development of atherosclerosis." (PMID 33679587, 2021). "Anti-VCAM-1 nanobodies were developed and conjugated to microbubbles to detect the VCAM-1 expression levels, both in mouse models of atherosclerosis and ex vivo human endarterectomy specimens." (PMID 33925941, 2021). "This study aimed to identify the expression patterns of miR-10a/GATA6/VCAM-1 in vivo and study their implications in the pathophysiology of human coronary artery disease (CAD), i.e., atherosclerosis." (PMID 34336268, 2021). "Another m6A writer, METTL14, has been shown to interact with FOXO1 and act directly on the promoter regions of VCAM-1 and ICAM-1, which enhanced the binding of monocytes to endothelial cells during atherosclerosis." (PMID 34869371, 2021). "TKIs have been shown to promote atherosclerosis by inducing the expression of pro-atherogenic adhesion molecules (CAM) on endothelial cells, including ICAM-1 (CD54), VCAM-1 (CD106) and E-Selectin (CD62E)." (PMID 34950060, 2021). "Vascular cell adhesion molecule-1 (VCAM-1), inter-cellular adhesion molecule-1 (ICAM-1), and E-selectin increase monocyte adhesion to the vascular wall, inducing atherosclerosis." (PMID 34960033, 2021). "Vascular cell adhesion molecule 1 (VCAM-1) is known to be overexpressed and translocated to the luminal surface of endothelial cells at the early stages of atherosclerosis." (PMID 32998422, 2020). "Vcam-1 staining was markedly reduced with NMP treatment, and, consistent with this, macrophage infiltration into sites of atherosclerosis, as assessed with CD68 staining, was also significantly reduced." (PMID 32669659, 2020). "Immunohistochemical analysis showed positive staining and significantly increased expression of NF-ĸB, VCAM1 and MMP9 proteins in the atherosclerosis group compared to the NC group (P < 0.05, P < 0.01)." (PMID 32213192, 2020). "Activated endothelial cells at sites of early atherosclerosis have been reported to show increased expression of P-selectin, ICAM-1, and VCAM-1." (PMID 33339328, 2020). "High expression levels of cell adhesion molecules (CAMs) such as VCAM-1, ICAM-1, and E-selectin by vascular endothelium are well correlated with atherosclerosis." (PMID 32066426, 2020). "Endothelial cell expression of VCAM-1 and ICAM-1 trigged by disturbed flow is one of the earliest events in atherosclerosis development preceding the presence of other markers of atherosclerosis such as monocyte recruitment." (PMID 31584065, 2020). "Sequentially, monocyte adhesion to endothelial cells was a crucial step in the early stages of atherosclerosis development, in which ICAM-1 and VCAM-1 were crucially involved." (PMID 33425996, 2020). "Adhesion and inflammatory molecules, such as VCAM-1 and intercellular adhesion molecules-1 (ICAM-1), are crucial players in the progression of atherosclerosis." (PMID 33510642, 2020). "Among the hub genes, TNF, PTPRC (also known as CD45), VCAM1, CD86 and MMP9 have been confirmed as inflammatory biomarkers of atherosclerosis." (PMID 32213192, 2020). "This study aimed at evaluating vascular cell adhesion molecule 1 (VCAM-1) and E-selectin serum concentrations, and atherosclerosis severity in patients with plaque psoriasis." (PMID 32942670, 2020). "Silencing of DNMT-1 by adenovirus-mediated DNMT shRNA inhibits the expressions of EC dysfunction-related proteins, including proliferating cell nuclear antigen, VCAM-1, and ICAM-1, and blocks the development of atherosclerosis." (PMID 31387590, 2019).
atherosclerosis (continued). "The most important mechanisms of GPx in the prevention and treatment of atherosclerosis stem from the inhibition of H2O2-mediated expression of MCP-1 and VCAM-1, in addition to an anti-inflammatory action." (PMID 31349600, 2019). "VCAM-1 and ICAM-1 have similar structures, but they are regulated by different mechanisms and show different functions at the initiation of lesions of atherosclerosis." (PMID 31452653, 2019). "In vascular inflammation, such as atherosclerosis, NF-κB upregulates the expression of adhesion molecules (ICAM-1and VCAM-1) and matrix-metalloproteases (MMP-2, and MMP-9), further exacerbating vascular inflammation." (PMID 31717401, 2019). "In the early phase of atherosclerosis, LPS, inflammatory cytokines, or oxidized LDL promotes the protein expression of adhesion molecules such as VCAM-1 and ICAM-1 and the secretion of monocyte chemoattractant protein 1 (MCP-1) in endothelial cells." (PMID 31248152, 2019). "VCAM-1 and ICAM-1 are induced in disease status including inflammation, atherosclerosis, vascular injury, and angiogenesis." (PMID 31575085, 2019). "Regarding ACS, some biomarkers have been investigated, including interleukins and adhesion molecules (VCAM-1 and ICAM-1), which are involved in the process of atherosclerosis and inflammation." (PMID 31778438, 2019). "In conclusion, we have shown that PGC-1α overexpression in skeletal muscle suppressed VCAM-1 and MCP-1 expression in the arterial wall and inhibited the progression of atherosclerosis." (PMID 30858489, 2019). "VCAM1, also known as CD106, is a transmembrane glycoprotein expressed in activated endothelium under a variety of pathologic conditions, including atherosclerosis and DKD." (PMID 31295940, 2019). "In the pathological process of atherosclerosis, TMAO accelerated endothelial dysfunction through the activation of PKC/NF-κB/VCAM-1." (PMID 31354519, 2019). "Knockout of Cx40 in mice causes increased atherosclerosis, inflammation, and vascular cell adhesion molecule-1 (VCAM-1) expression; VCAM-1 is involved in recruitment of monocytes during atherosclerosis." (PMID 29543751, 2018). "For instance, beta-sitosterol, a common ingredient of Arum ternatum Thunb and Zingiber officinale Roscoe, has inhibitory effects on the expression of VCAM-1 and ICAM-1, which promote atherosclerosis by regulating the chronic inflammatory process." (PMID 29861771, 2018). "Upregulation of miR-155 can promote several pro-inflammatory processes, including leukocyte adhesion to the endothelium by enhancing the expression of VCAM-1 and ICAM-1, leading to atherosclerosis." (PMID 29642385, 2018). "Immune cells derived IL-6 and TNF-α induce endothelium damage and increased expression of vascular cell adhesion molecule-1 (VCAM-1) and intercellular adhesion molecule-1 (ICAM-1), consequently triggering atherosclerosis development." (PMID 30305178, 2018). "In response to inflammatory stimuli, vascular endothelial cells express a number of adhesion molecules that mediate early leukocyte attachment and atherosclerosis progression, particularly, such as ICAM1, VCAM1 and E‐selectin." (PMID 29512862, 2018). "We also measured levels of COX2, VCAM1, CD68, SM22, Bcl2 mRNAs and of atherosclerosis/inflammation -related miRs 21-5p, 125a-5p, 126-5p, 146-5p, 155-5p and 424-5p, to compare the inflammation and apoptosis levels among plaque material." (PMID 28472949, 2017). "Endothelial dysfunction and upregulation of VCAM-1 and MCP-1 are critical events in atherosclerosis, which recruits macrophages into intima and contributes to the initiation of atherosclerosis." (PMID 28300760, 2017). "Since plasma lipids and the inflammatory state were elevated (typical baseline levels for SAA and VCAM-1 are <10μg/ml and <2μg/ml respectively) in both LFD- and HFD-fed mice, both groups developed atherosclerosis." (PMID 28678821, 2017).
atherosclerosis (continued). "The authors selected E-selectin, P-selectin, VCAM-1, ICAM-1 and MCP-1 cytokines as endothelial dysfunction biomarkers related to the early stages of atherosclerosis." (PMID 28335517, 2017). "VCAM1 and SELE were regulated in the same manner by atherosclerosis-prone low laminar flow (1 dyn/cm2)." (PMID 28432984, 2017). "Herein, ICAM-1, VCAM-1, MCP-1, TNF-α, IL-1β, and MMPs-9, which participate in initial and later stages of atherosclerosis, will be more elaborately discussed." (PMID 29038791, 2017). "Subsequently, we further determined two inflammatory molecules, VCAM-1 and MCP-1, which contributed to macrophage migration and atherosclerosis." (PMID 28300760, 2017). "Additionally, the lack of insulin receptor gene and resulting attenuation of insulin signaling were shown to increase the expression of vascular cell adhesion molecule 1 (VCAM-1), a strong inducer of atherosclerosis, showing that loss of insulin signaling could accelerate atherosclerosis." (PMID 27247938, 2016). "The citrus flavonoids, naringin, and naringenin, were found to significantly lower the expression levels of vascular cell adhesion molecule-1 (VCAM-1) and monocyte chemotactic protein-1 (MCP-1), with potential applications in the prevention of atherosclerosis." (PMID 28231183, 2016). "Endothelial cells also express adhesion and chemoattractant molecules such as MCP-1, VCAM-1, and ICAM-1, which recruit inflammatory monocytes into the vascular wall and initiate atherosclerosis." (PMID 27190988, 2016). "Interleukin-6, TNF-α, VCAM1, ICAM1 and MCP-1 are important inflammatory cytokines that are engaged in the development of atherosclerosis, which can exacerbate it." (PMID 25661015, 2015). "One early phase of atherosclerosis involves the firm adhesion of inflammatory cells to ECs as well, whose process is mainly mediated by ICAM-1 and VCAM-1." (PMID 25582325, 2015). "VCAM-1, and ICAM-1 and E-sel are well-known inflammatory mediators involved in pathogenesis of atherosclerosis." (PMID 25632270, 2015). "The released NF-κB dimers enter the nucleus and activate the expression of many genes involved in the initiation and progression of atherosclerosis, including cytokines (e.g., TNF, IL-6), adhesion molecules (e.g., VCAM-1, ICAM-1) and chemokines (e.g., MCP-1)." (PMID 26322890, 2015). "The purpose of this study is to determine if inflammation, i.e. VCAM-1 expression, is a better diagnostic tool of early plaque development than other markers of atherosclerosis, including EDD, and in addition if peripheral VCAM-1 can predict the extent of CAD." (PMID 26702331, 2015). "With regards to the use as early markers of disease, VCAM-1 and ICAM-1 have been demonstrated to be transcriptionally upregulated on the endothelium of mouse models of atherosclerosis during the very early stages of disease development." (PMID 25938969, 2015). "VCAM-1 seems to have a more crucial role than ICAM-1 in mechanisms leading to increased LVMI, i.e. atherosclerosis and hypertension." (PMID 26398099, 2015). "The NP-mediated vascular effects include expression of endothelial cell adhesion molecules such as intercellular adhesion molecule 1 (ICAM-1) and vascular cell adhesion molecule 1 (VCAM-1), vasomotor dysfunction and accelerated progression of atherosclerosis." (PMID 25184212, 2014). "The most important adhesion molecules involved in atherosclerosis appear to be endothelial cell selectin (E-selectin), intercellular cell adhesion molecule (ICAM)-1, and vascular cell adhesion molecule (VCAM)-1." (PMID 25045892, 2014). "Several markers, such as VCAM-1, ICAM-1, and von Willebrand factor antigen, have been shown to reliably indicate the increased activation of endothelial cells in atherosclerosis." (PMID 25374442, 2014). "This suggest that the treatments of G1 and PCA can effectively down-regulate the inflammatory markers (VCAM-1 and CD40) and up-regulate GPER-1 and CD31 to attenuate atherosclerosis for both short and long term." (PMID 25411835, 2014).
atherosclerosis (continued). "PGRN also played a protective role in atherosclerosis through suppressing TNFα-induced expression of ICAM-1 and VCAM-1 in endothelial cells." (PMID 24651300, 2014). "Transcriptional screening of ACE-overexpressing monocytes revealed noticeably increased expression of Angiotensin II receptors and adhesion- as well as atherosclerosis-related ICAM-1 and VCAM1." (PMID 25003524, 2014). "Adhesion molecules such as VCAM-1 and ICAM-1 play a significant role in the process of atherosclerosis as they ensure the recruitment of inflammatory cells." (PMID 24062791, 2013). "Damaged endothelial cells, arterial lesions from atherosclerosis experiment model and human all show increased expression of these molecules including E-sel, ICAM-1, VCAM-1 and MCP-1." (PMID 23895132, 2013). "The preclinical study with aortic pouch biopsy specimens from humans with atherosclerosis and diabetes shows intense immunostaining for SREBP-1 and the inflammatory marker VCAM-1 in atherosclerotic plaques." (PMID 23825667, 2013). "The significant reduction of elevated VCAM-1, MCP-1, TNF-α, IL-17 in atherosclerosis model of hypercholesterolemia rabbit shows the effect of clopidogrel on such inflammatory markers." (PMID 24455725, 2013). "Because expression of VCAM-1 reflects an inflammatory state in human atherosclerosis, the clinical relevance of elevated SREBP-1 to vascular inflammation is evidenced by overlapped staining of SREBP-1 with VCAM-1 in atherosclerotic plaques in humans." (PMID 23825667, 2013). "Given the role of adhesion molecules in the pathogenesis of atherosclerosis, we investigated the effect of ICAM-1 and VCAM-1 in our present analysis." (PMID 23826202, 2013). "VCAM-1 and ICAM-1 are thought to play an important role in the process of atherosclerosis by recruiting inflammatory cells, and they are both are upregulated by pro-atherogenic factors." (PMID 24364887, 2013). "Accumulating evidence suggests that the induction of VCAM-1 or ICAM-1 by TNF-α in endothelium is mediated by the activation of MAPK and transcription factors such as NF-κB, leading to the pathogenesis of atherosclerosis." (PMID 23401716, 2013). "It is well established that E-sel, VCAM-1, ICAM-1 and MCP-1are key molecules involved in the initiation of inflammation pathogenesis of atherosclerosis, they collaboratively promote the adhesion of monocytes and then the migration to endothelium." (PMID 23895132, 2013). "Proinflammatory cytokines and adhesion molecules, such as vascular cell adhesion molecule (VCAM)-1 and intercellular cell adhesion molecule (ICAM)-1, induce atherosclerosis by NF-κB activation." (PMID 22645626, 2012). "Circulating endothelial adhesion molecules, VCAM-1 and ICAM-1, were supposed to be early markers of atherosclerosis." (PMID 22919307, 2012). "Expression levels of VCAM-1 and ICAM-1 were largely studied in a mouse model of atherosclerosis, and these molecules were upregulated by a high-cholesterol diet in an animal model." (PMID 22645626, 2012). "In atherosclerosis, the interaction of macrophage very late antigen-4 (VLA-4) and endothelial VCAM-1 mediates monocyte firm adhesion." (PMID 22291917, 2012). "There were statistically significant reductions in the levels of ICAM-1, VCAM-1 and CRP at the end of treatment with water extract in group 500 mg/kg compared to atherosclerosis group." (PMID 21214952, 2011). "In the atherosclerosis group there were significant increase between 0 times and end time for all ICAM-1, VCAM-1 and CRP." (PMID 21214952, 2011). "The most important adhesion molecules involved in atherosclerosis appear to be intercellular cell adhesion molecule-1 (ICAM-1), endothelial cell selectin (E-selectin) and vascular cell adhesion molecule-1 (VCAM-1)." (PMID 18955365, 2011).
atherosclerosis (continued). "The unaltered expression of ICAM-1 and VCAM-1 corresponds well with the unaltered ICAM-1 and VCAM-1 mRNA levels in the CB exposed mice of either age group as well as the unchanged progression of atherosclerosis in the aged CB exposed mice." (PMID 21054825, 2010). "To further analyze cellular and molecular mediators in the progression of atherosclerosis, we quantified the amount of lipids, macrophages, T cells, as well as of the adhesion molecules ICAM-1 and VCAM-1 in plaques from the aortic sinus." (PMID 21042583, 2010). "VCAM-1 and ICAM-1 also play important roles in the process of atherosclerosis as they are vital to leukocyte attachment, rolling, and trans-endothelial migration." (PMID 19997643, 2009). "Because pathological activation of ECs leads to excessive recruitment of leukocytes to the vascular endothelium and is a key event in atherosclerosis progression, we quantified the impact of Gm39822 on the expression of VCAM-1 (vascular cell adhesion molecule-1) and monocyte recruitment to ECs." (PMID 40943070, 2025). "An unannotated disease-specific cell cluster (A-cluster 6) co-expressed contractile VSMC markers (Myh11, Acta2, and Cnn1) with several atherosclerosis-induced ECM genes (Col1a1, Mgp, Eln, Fn1, Col4a1, and Col8a1) and had reduced levels of Ly6a, Vcam1, and Tnfrsf11b compared to imVSMCs." (PMID 40577585, 2025). "In several studies, levels of VCAM-1, ICAM-1, and E-selectin have been correlated with inflammatory processes in the endothelium (e.g., overexpression of VCAM-1 and ICAM-1 in the early stages of atherosclerosis)." (PMID 41373705, 2025). "In the early stages of atherosclerosis, endothelial cells are activated and express intercellular adhesion molecule-1 (ICAM-1) and vascular adhesion molecule-1 (VCAM-1), which attract lymphocytes and monocytes to bind and infiltrate the arterial wall, leading to an inflammatory reaction." (PMID 40606622, 2025). "In the current study, ATO and BA significantly decreased the level of MCP-1 (p < 0.01), VCAM-1 (p < 0.01) and MMP9 (p < 0.05), indicating that BA may play a positive role in preventing the formation and development of atherosclerosis." (PMID 40529499, 2025). "In light of studies showing that FOXP1 can transcriptionally repress the NLRP3 inflammasome and inhibit the development of atherosclerosis, we hypothesized that CtBP1 might interact with FOXP1 to modulate VCAM‐1 and ICAM‐1 gene transcription." (PMID 39949978, 2025). "Atherosclerosis is initiated by the accumulation of oxidized low-density lipoprotein (oxLDL), which triggers endothelial cell activation and upregulation of adhesion molecules, such as intercellular adhesion molecule-1 (ICAM-1), VCAM-1, and P-selectin, etc.." (PMID 41011157, 2025). "Endothelial dysfunction, characterized by the impaired function of the cells lining the blood vessels, is regarded as an early indicator of atherosclerosis development, often identified by an increased expression of adhesion molecules such as ICAM-1 and VCAM-1." (PMID 38915995, 2024). "Furthermore, butyrate treatment of Ea.hy926 cells has been found to reduce ox-LDL uptake, CD36, VCAM-1, TNF-α, and interleukin-1β/6 production while increasing IL-10 production, suggesting its potential as a treatment for atherosclerosis." (PMID 39275259, 2024). "Overexpression of COX-2 enhances the expression of intercellular adhesion molecule-1 (ICAM-1) and vascular cell adhesion molecule-1 (VCAM-1), facilitating the recruitment of inflammatory cells to the vascular wall, further accelerating the development of atherosclerosis." (PMID 39517211, 2024). "In conclusion, we propose a mechanistic pathway in which the interaction between integrin α9β1 and VCAM-1 may mediate neutrophil recruitment followed by enhanced NETosis, most likely via the ERK signaling cascade, thereby promoting early atherosclerosis." (PMID 39036986, 2024).